ANXA13 (annexin A13)
Description:
[Isoform A]: Binds to membranes enriched in phosphatidylserine or phosphatidylglycerol in a calcium-dependent manner. Half-maximal membrane binding requires about 60 uM calcium. Does not bind to membranes that lack phospholipids with an acidic headgroup. [Isoform B]: Binds to membranes enriched in phosphatidylserine or phosphatidylglycerol in a calcium-dependent manner, but requires higher calcium levels for membrane binding than isoform A. Half-maximal membrane binding requires about 320 uM calcium.
Synonyms: ISA; ANX13
Tractability: Antibody: UniProt places it where antibodies can reach, with high confidence; its Gene Ontology location is reachable by antibodies, with high confidence; the Human Protein Atlas places it where antibodies can reach.
Gene: Protein-coding gene on chromosome 8 (123,680,794 to 123,737,414, reverse strand). Ensembl gene ENSG00000104537.
Subcellular location: Apical cell membrane; Cell membrane; Cytoplasmic vesicle
Subcellular location (Human Protein Atlas): Plasma membrane; Nucleoplasm
Gene Ontology:
Molecular function: calcium ion binding; calcium-dependent phospholipid binding; phosphatidylglycerol binding; phosphatidylserine binding
Biological process: cell differentiation
Cellular component: apical plasma membrane; extracellular exosome; extracellular region; membrane; plasma membrane; cytoplasmic vesicle; nucleus; vesicle membrane
Genetic constraint (gnomAD): Loss-of-function variants: 32 observed, 44.77 expected, observed/expected ratio (o/e) 0.71, 90% interval 0.54 to 0.96. The upper end of that interval is the gene's LOEUF score, 0.96, which puts it in group 4 of 6, group 1 being the genes least tolerant of losing a copy. Missense variants: 397 observed, 398.25 expected, observed/expected ratio (o/e) 1, 90% interval 0.92 to 1.08. Synonymous variants: 158 observed, 154.99 expected, observed/expected ratio (o/e) 1.02, 90% interval 0.89 to 1.16.
Homologues: Orthologues: chimpanzee ANXA13 (99% identical), macaque ANXA13 (97% identical), dog ANXA13 (91% identical), rabbit ANXA13 (89% identical), pig ANXA13 (88% identical), guinea pig ANXA13 (87% identical), mouse Anxa13 (87% identical), rat Anxa13 (86% identical), tropical clawed frog anxa13 (66% identical), zebrafish anxa13l (53% identical), Drosophila melanogaster AnxB9 (49% identical), Drosophila melanogaster AnxB11 (45% identical), and 1 more. Paralogues in human: ANXA7 (49% identical), ANXA8 (48% identical), ANXA8L1 (48% identical), ANXA11 (47% identical), ANXA4 (46% identical), ANXA6 (46% identical), ANXA1 (44% identical), ANXA5 (43% identical), ANXA2 (43% identical), ANXA3 (42% identical), ANXA10 (35% identical), ANXA9 (31% identical).
Diseases named in the same sentence as ANXA13 in open-access papers:
ANXA13 is named in the same sentence as 25 diseases in open-access papers, as found by Europe PMC text mining. Sharing a sentence is not in itself a finding about the gene and the disease. The quoted sentences say what the papers report.
colorectal cancer (3 papers, 2016 to 2023). A primary or metastatic malignant neoplasm that affects the colon or rectum. "Similarly, ANXA13 expression is upregulated in colorectal cancer and promotes the invasion of cancer." (PMID 36936694, 2023). "Except ANXA9 and ANXA13, changes in the expression of individual ANXs were observed in a diversity of cancers, including gastric carcinoma, colorectal cancer, pancreatic cancer, breast cancer, glioma, kidney cancer, hepatocellular, carcinoma, melanoma, but not in cervical cancer." (PMID 27402115, 2016).
breast carcinoma (2 papers, 2016 to 2022). "ANXA13 was identified as a regulator of chemotherapy resistance because ectopic overexpression of ANXA13 could increase the sensitivity of malignant breast cancer cells to rapamycin." (PMID 39290334, 2022).
gastric cancer (2 papers, 2016 to 2018). A primary or metastatic malignant neoplasm involving the stomach. "Among the top 10 DRGs for Chinese (GSE54129), six genes have been reported to be gastric cancer (GC) related (REG4, ANXA13, C7, ASS1, MSMB, CREB1) and the rest four were directly regulated by known gastric cancer genes in our GRNs, in which two genes are also cancer related (BPTF, CLCA1)." (PMID 29745833, 2018).
bladder cancer (1 paper, 2021). "We used the TCGA database to analyze the mRNA expression of ANXA1–11 and ANXA13 in bladder cancer tissues and normal tissues." (PMID 34484309, 2021). "The expression of ANXA1, ANXA2, ANXA3, ANXA5, ANXA6, ANXA8, and ANXA13 was closely related to basal-subtype bladder cancer, while the expression of ANXA4, ANXA9, ANXA10, and ANXA11 was closely related to luminal-subtype BC." (PMID 34484309, 2021). "Similarly, the expression of ANXA9–11 and ANXA13 in high-grade bladder cancer was lower than that in low-grade bladder cancer." (PMID 34484309, 2021).
colon adenocarcinoma (1 paper, 2017). "Interestingly ANXA13 is highly expressed in the human colon adenocarcinoma cell line HT29, suggesting that ANXA13 might be clinically relevant in CRC." (PMID 28423508, 2017).
fatty liver disease (1 paper, 2024). A reversible condition wherein large vacuoles of triglyceride fat accumulate in liver cells via the process of steatosis. "Among downregulated genes (KIT, NTRK2, MAMDC2, and ANXA13), KIT could regulate apoptosis, NTRK2 was revealed that capable of activating apoptosis pathways with Brain derived neurotrophic factor (BDNF), which may promote the progression of fatty liver disease." (PMID 38665091, 2024).
lipid metabolism disorders (1 paper, 2024). "However, the functions of MAMDC2 and ANXA13 in lipid metabolism disorders are still unclear." (PMID 38665091, 2024).
lung adenocarcinoma (1 paper, 2022). A carcinoma that arises from the lung and is characterized by the presence of malignant glandular epithelial cells. "In addition, increased expression of ANXA13 could promote the proliferation and migration of lung cancer cells in vitro and was associated with poor survival in lung adenocarcinoma patients." (PMID 35205125, 2022).
lymph node metastasis (1 paper, 2017). "In CRC patients, ANXA13 expression levels correlated with lymph node metastasis and were associated with poor overall survival." (PMID 28423508, 2017). "In human patients, ANXA13 upregulation is associated with lymph node metastasis and poor survival." (PMID 28423508, 2017). "However, there was a significant association between annexin A13 expression and lymph node metastases (p=0.003)." (PMID 28423508, 2017). "ANXA13 is associated with CRC cell invasion in vitro, and with lymph node metastasis and poor survival in CRC patients." (PMID 28423508, 2017). "In the current study, we have shown that annexin A13 expression was positively correlated with lymph node metastasis in 125 patients with CRC." (PMID 28423508, 2017).
ovarian carcinoma (1 paper, 2019). A malignant neoplasm originating from the surface ovarian epithelium. "In addition, the expression levels of ANXA1, ANXA4, ANXA5, ANXA6, ANXA7 and ANXA13 were lower in ovarian cancer than in the normal controls." (PMID 31474227, 2019). "Therefore, genetic variations in ANXA9 and ANXA13 genes may be correlated with ovarian cancer tumorigenesis and progression." (PMID 31474227, 2019).
ovarian serous cystadenocarcinoma (1 paper, 2019). A malignant serous cystic epithelial neoplasm arising from the ovary. "The TCGA database confirmed that ANXA4 expression was downregulated in ovarian serous cystadenocarcinoma (P = 4.81E−6, fold change = − 2.019) and that ANXA13 was downregulated in malignant tumor tissues (P = 1.68E−4, fold change = − 9.347)." (PMID 31474227, 2019).
cancer (11 papers, 2016 to 2024). A tumor composed of atypical neoplastic, often pleomorphic cells that invade other tissues. "Among 12 annexin A isoforms (annexin A1-11 and annexin A13), annexin A5 in particular has unphosphorylated short N-terminus which enables this protein to exhibit a wide range of functions such as signalling, cancer cell growth, and invasion." (PMID 38249992, 2024). "Results obtained for FBXO32, ZHX1 and ANXA13 genes encoded within the same region as ATAD2 clearly emphasize the specificity of ATAD2 and MYC as well as ATAD2 and cancer stemness associations." (PMID 35049055, 2022). "In the 8-mRNA signature (KCNJ18, RPE65, GRIA1, LCN15, C11orf21, ANXA13, FSIP2 and KRT76), the expressions of some mRNAs have been reported to have significant associations with the survival in some cancers." (PMID 35675043, 2022). "Nevertheless in the few studies performed related to the effect of ANXA9 and ANXA13 in tumour demonstrated ANXA9 and ANXA13 could promote invasion and metastasis in a certain types of cancers." (PMID 37464398, 2023). "There are limited studies available that focus on ANXA13 in cancer." (PMID 39290334, 2022). "Upon close examination, annexin A13 was expressed mainly in the cytoplasm of cancer cells." (PMID 28423508, 2017). "To uncover the potential molecular pathways underlying ANXA13-enhanced tumor cell invasion and migration, we determined whether the ANXA13 downstream protein MMP-9, which is known for its role in cancer metastasis and tumor cell migration and invasion, is involved in the process." (PMID 28423508, 2017). "Expression of the annexin family had beenstudied in a wide range of cancers, including ANXA1, ANXA2 and ANXA13 Annexin familymembers were involved in signal transduction, cellular differentiation,proliferation and thus in tumorigenesis (Lizarbe etal., 2013)." (PMID 38626574, 2024). "It is not clear whether annexin A13 has an opposite function in different types of cancers." (PMID 28423508, 2017).
tumor (3 papers, 2017 to 2023). "To elucidate whether ANXA13 overexpression is associated with tumor invasion and metastasis in human patients, we investigated annexin A13 expression in human CRC tissues and its relationship with clinicopathological factors." (PMID 28423508, 2017). "To determine its clinical value in CRC, we used a panel of CRC cell lines to investigate the expression level of ANXA13 in these cells and their potential roles in tumor development." (PMID 28423508, 2017). "Moreover, our in vitro study using CRC cell lines indicated that CRC tumor cell invasion was enhanced by ANXA13 overexpression in SW620 cells but decreased by ANXA13 siRNA-mediated downregulation in HCT116 cells." (PMID 28423508, 2017). "Importantly, our results suggest that ANXA13 enhances tumor cell invasion through activation of the AKT-MMP-9 pathway, since the AKT inhibitor LY29004 abolished ANXA13-enhanced tumor cell invasion." (PMID 28423508, 2017). "Tumor cell invasion was determined by a Matrigel in vitro invasion assay in selected CRC cells with either upregulated (via plasmid transfection) or downregulated (via siRNA treatment) expression of ANXA13." (PMID 28423508, 2017). "Our in vitro experiments in cultured CRC cells strongly suggest that ANXA13-mediated the expression of the active form of MMP-9, which is known for its role in tumor metastasis." (PMID 28423508, 2017). "We observed that annexin A13 was not expressed in normal epithelial cells, but expressed at moderate or high level in tumor cells in 58.4% (73/125) of CRC cases." (PMID 28423508, 2017). "We found that annexin A13 expression was not correlated with tumor stage, tumor differentiation, gender or age." (PMID 28423508, 2017). "Therefore, it is possible that ANXA13-mediated activation of AKT and MMP-9 plays a pivotal role in tumor cell invasion and metastasis in CRC." (PMID 28423508, 2017). "Although resulting in a significant effect on tumor cell migration and invasion, ANXA13 overexpression showed no apparent effect on tumor cell proliferation as shown by MTT assays." (PMID 28423508, 2017).
ANXA13 also shares sentences with these, for which no sentence is quoted: acute kidney injury (1 paper); autoimmune disease (1); bladder tumors (1); cervical cancer (1); dry eye (1); glioma (1); kidney cancer (1); lung carcinoma (1); melanoma (1); mouth (1); pancreatic cancer (1); Sjögren’s Syndrome (1).